CXCL1 (C-X-C motif chemokine ligand 1)
Diseases named in the same sentence as CXCL1 in open-access papers (continued):
Sharing a sentence is not in itself a finding about the gene and the disease.
tumor (continued). "Moreover, tumor-derived SPP1 promoted neutrophil-dominant PMN formation by specifically targeting lung epithelial cells to secrete CXCL1 and subsequently boosted HCC lung metastasis through NETs formation." (PMID 39529085, 2024). "CXCL1 is chemotactic of CXCR2 expressing CAR T-cells toward the tumor." (PMID 38612592, 2024). "Moreover, we showed that CXCL1 chemokine proved to be a strong candidate as a tissue differentiating biomarker and tumor histological stage indicator from patients’ serum." (PMID 38175424, 2024). "CXCL1, a member of the CXCL chemokine family, is involved in various stages of tumor progression, such as the regulation of immune cell activity, tumor cell proliferation, invasion, metastasis, and formation of tumor-associated microvasculature." (PMID 38791448, 2024). "However, there has been no comprehensive overview summarizing the complete understanding of CXCL1 in tumor processes." (PMID 38673949, 2024). "Interestingly, in our study, we found that hydrogen treatment actually alleviated ROS in CAFs and down‐regulated a key ROS‐induced gene, Nos2, and down‐stream pro‐tumor factors such as Mmp2, Cxcl1, and Cxcl12." (PMID 38757665, 2024). "While IL-1α KO tumors contained lower levels of chemokines, such as CCL2 and CXCL1/2/3, known to attract MDSCs into the tumor, they showed higher expression of CCL5, CXCL9/10, which could attract T lymphocytes and NK cells." (PMID 38612760, 2024). "In cSCC, there is elevated CXCL1 expression in the tumor compared to healthy skin." (PMID 38673949, 2024). "Importantly, although tumor cells secrete chemokines like CXCL1/2, CCL2, and IL-8 that attract myeloid cells to the tumor microenvironment (TME), they typically do not secrete chemokines for which CAR T-cells express receptors." (PMID 39317919, 2024). "For example, TAMs release CSF-1 and CXCL1 helping tumor migration and EMT." (PMID 39104525, 2024). "Importantly, silencing CXCL1 in the tumor cells reprogramed neutrophils, controlling tumor growth in a T cell-dependent manner." (PMID 38786066, 2024). "Furthermore, our findings indicate CXCL1 chemokine as a strong candidate as a tissue differentiating biomarker and tumor histological stage indicator from patients’ serum, and IL1b overexpression as a molecular factor related to increased TNM stage." (PMID 38175424, 2024). "Thus, CXCL1’s roles in angiogenesis and neutrophil attraction highlight how tumor cells utilize it in order to remake the PDAC TME to their advantage." (PMID 38339310, 2024). "CXCL1 plays a critical role in cancer include induction of cancer cell migration, lymph node metastasis, recruitment of granulocytic myeloid derived suppressor cells into the tumor niche, tumor angiogenesis and recruitment of regulatory T cells to the TME." (PMID 38393465, 2024). "Tumor-derived CXCL1 has been reported to promote malignant behavior by polarizing macrophages." (PMID 38713320, 2024). "The level of CXCL1 expression increases with HCC tumor growth." (PMID 37408240, 2023). "As observed in different tumours, CXCL1 promotes tumour cell growth and EMT." (PMID 37037815, 2023). "Moreover, tumor‐derived CXCL1 and CXCL8 increased CXCR2, ERK and JNK pathways‐dependent production of VEGFA and MMP9 in neutrophils, which led to lymphangiogenesis." (PMID 36670069, 2023). "CXCL1 expression enhances the recruitment of Tregs to facilitate the immune escape of the tumour." (PMID 37627054, 2023). "CXCL1 expression in ESCC tumors is correlated with tumor size." (PMID 37408240, 2023). "CXCL1 (membrane-bound/secreted) can potentially regulate tumor-related inflammatory response." (PMID 37770496, 2023). "Furthermore, they observed strong spatial contiguity between CXCL1-expressing tumor islands and CXCR2+ PMN-MDSCs, with CD8+ T cells being conspicuously absent from these areas." (PMID 37455286, 2023).
tumor (continued). "In addition, metformin activates NK cells infiltrated to the tumor accompanied with high perforin production through mTOR inhibition that subsequently suppresses CXCL1 production in an AMPK-independent manner but is dependent on the mTOR and pSTAT1 pathways." (PMID 37686159, 2023). "CXCL1 is involved in the recruitment of various cells to the tumor niche." (PMID 37108425, 2023). "Higher CXCL1 expression in a tumor means a worse prognosis for patients." (PMID 37408240, 2023). "Additionally, it was demonstrated that tumor derived exosomes carry RNA to the type II alveolar cells of the lung stimulating expression of CXCL1, CXCL2, CXCL5 and CXCL12, through engagement with the toll like three receptor (TLR3), which recruit neutrophils." (PMID 36910138, 2023). "Our results also revealed an important issue: selective HDAC6is could suppress tumour migration and invasion by inhibiting CXCL1 induction in irradiated cancer." (PMID 36810912, 2023). "Nevertheless, we asked whether genetically ablating Cxcl1 in qMCP−/−;Ntv-a mice can extend the survival of Nf1-tumor-bearing mice." (PMID 37012245, 2023). "It was also confirmed that CXCL1 levels in the tumor and peripheral blood were both significantly increased under CUMS, and clodronate liposomes administration could block CUMS-induced CXCL1 upregulation." (PMID 37210553, 2023). "In BC, CXCL1 has been recognised as a marker for tumour invasion." (PMID 36810912, 2023). "STING activation enhanced neutrophil migration into the tumor in an NF-κB/CXCL1/2-dependent manner." (PMID 36980689, 2023). "However, they noted a correlation between high CXCL1 expression and higher tumor grade, metastases, and shorter relapse-free survival." (PMID 37370728, 2023). "Besides, CAFs, major sources of chemokines, including CXCL12, CCL2 and CXCL1, can recruit MDSCs to tumor sites and promote their differentiation and activation." (PMID 37046312, 2023). "This receptor guides myeloid-derived cells from the bone marrow to CXCL1-overexpressing tumor sites, where they facilitate tumor immune evasion by suppressing the proliferation, activation, and motility of effector T cells and promoting the numerical expansion of Tregs." (PMID 37865804, 2023). "Furthermore, the activation of NF-κB stimulates the production of the potent chemokine CXCL1, which, in turn, facilitates the recruitment of MDSCs to the tumor site, ultimately leading to the suppression of CD8+T cell infiltration." (PMID 37865804, 2023). "On the contrary, HSPA1A, SERPINA1 and CXCL1 are highly expressed in tumor tissues." (PMID 37950156, 2023). "Moreover, enriched immunoregulatory signaling and increased CD4+ and CD8+ T cells were observed in Cxcl1-silenced tumors, suggesting that Cxcl1 silencing overcomes T-cell exclusion and suppresses tumor growth through a CD8+ T-cell mechanism." (PMID 37455286, 2023). "In vivo studies using anti-TIM-3 monoclonal antibodies have shown that it is possible to effectively inhibit tumor growth by restoring effector T cell function and reducing the recruitment of myeloid-derived suppressor cells to tumor microenvironment in a CXCL1-dependent manner." (PMID 37567938, 2023). "In addition, we confirmed that the serum levels of CXCL1 and GM‐CSF in Setd2KO tumor‐bearing mice were also greatly increased." (PMID 36453584, 2023). "Given that neutrophil influx and Cxcl1 expression were increased in tumors generated in qMCP−/−; Ntv-a mice, we reasoned that genetic deletion of Cxcl1 in qMCP−/−; Ntv-a mice might reverse these phenotypes and prolong the survival of tumor-bearing mice." (PMID 37012245, 2023). "In the tumor niche, myofibroblasts, tumor-associated dendritic cells (TADC), and TAM may also be responsible for CXCL1 production, with various factors responsible for CXCL1 expression in these cells." (PMID 37408240, 2023).
tumor (continued). "Promoting tumor cell recognition by DCs can up-regulate the expression of chemokines, such as chemokine (C-X-C motif) ligand 1 protein (CXCL1) and chemokine (C-X-C motif) ligand 5 protein (CXCL5), and increase the infiltration and proliferation of immune cells at the site of tumor." (PMID 37040283, 2023). "As SLC25A22 knockout reduced MDSC infiltration, we hypothesized that SLC25A22 is required for tumor-induced MDSC chemotaxis through CXCL1/3." (PMID 37542037, 2023). "It inhibited the proliferation and migration of tumor cells by downregulating CXCL1 and ITGA2." (PMID 37745305, 2023). "CXCL1 also acts on G-MDSC, causing their recruitment to the tumor niche." (PMID 37108425, 2023). "Additionally, MMPs promote the release of many other cytokines and growth factors supporting tumorigenesis, such as vascular endothelial growth factor (VEGF), which promotes tumor-driven angiogenesis, and the chemokine CXCL1, which promotes tumor growth." (PMID 36945046, 2023). "High plasma levels of CXCL1 along with TGF-β in patients with metastatic breast cancer were also associated with increased detection of circulating tumor cells (TGF-β p < 0.0001; CXCL1 p = 0.02) and shorter overall survival (CXCL1 p = 0.05; CXCL1+ TGF-β p = 0.001)." (PMID 37370728, 2023). "In addition, CXCL1/2/5/8 are also responsible for the recruitment of circulating neutrophils to the tumor." (PMID 37174093, 2023). "Inhibition of P300 activity blocked NF-κB activation and CXCL1-induced pro-tumor growth effects." (PMID 36434686, 2022). "Specifically, only CXCL1 changed in the peripheral blood of patients in the tumor recurrence group." (PMID 36254009, 2022). "In addition, activation of the CXCL1/CXCR2 signaling axis was also observed to promote tumor angiogenesis and progressive growth by activating STAT3 and enhancing VEGF levels." (PMID 36612163, 2022). "CXCL1 inhibition significantly attenuated tumor growth and metastatic lung nodule formation." (PMID 36552865, 2022). "Although other members of the CXCR2 ligand family, i.e., CXCL7 and CXCL5, have frequently been reported to promote the progression of CCA, our present results indicate that CXCL1 may exert a tumor-inhibitory effect on CCA cells." (PMID 35377900, 2022). "Moreover, CXCL1 inhibition rKLK6-mediated tumor growth and metastatic lung module formation in KLK6−/− mice injected with B16F10." (PMID 36552865, 2022). "Another study demonstrated that excess circulation of CXCL1 leads to a reduction in an extracellular matrix tumor-suppressor protein fibulin-1 through NF-κB/Histone Deacetylase 1 (HDAC1) epigenetic regulation, which facilitates the invasion and metastasis of CRC cells." (PMID 35954156, 2022). "In addition, PDAC upregulates necroptosis complex component receptor-interacting serine/threonine-protein 1 (RIP1) in both tumor epithelial cells and stroma to induce chemokine CXCL1 expression, which attracts macrophage infiltration." (PMID 36230914, 2022). "Furthermore, CXCL-1-receptor CAR-T cells that target the chemokine CXCL-1 derived from melanoma have proven to be effective in directing effector CAR-T cells toward tumor sites." (PMID 35326556, 2022). "Nevertheless, it is of great interest to investigate whether CXCL14 can act as an antagonist to the well-established CXCL1/5/8-CXCR2 signaling in the tumor microenvironment." (PMID 36012586, 2022). "Moreover, tumor-secreted CXCL1 contributes to the modification of neutrophil behavior and drives NDNs to an LDN-like phenotype." (PMID 36555469, 2022). "In the CT26 tumour model, we identified early levels of CXCL1, CCL2 and CCL17 as having important roles in predicting tumour growth as well as similar pairwise correlations with factors directly correlating with tumour growth and one another, suggesting they played similar roles in this context." (PMID 35226704, 2022).
tumor (continued). "Furthermore, we showed that the increase in tumor-infiltrating myeloid CD45+ cells and the amount of circulating cytokine IL-6 and chemokine KC (also known as CXCL1) is associated with a higher tumor size in different strains." (PMID 36037073, 2022). "Tumor-infiltrating mast cells promote tumor growth through the release of IL −1β and blood microvessel formation through CXCL1 and VEGF-A; they promote cancer metastasis through the release of IL −8 and suppress T-cell immunity to cancer through the expression of programmed death-ligand 1 (PD -L1)." (PMID 35266441, 2022). "The analysis showed a decrease in CXCL1 expression with the progression of tumor stage." (PMID 36434686, 2022). "Since CXCL1,2,5 and 8 bind to the chemokine receptor CXCR2 which is associated with neutrophil recruitment to tumours, we first confirmed that Cxcr2 is indeed highly expressed in metastasis infiltrating neutrophils and that CXCR2 expression is not affected by gemcitabine treatment." (PMID 35022267, 2022). "We found that specific overexpression of CD147 in the epidermis (EpiCD147-OE) induces spontaneous tumor formation; moreover, a set of chemokines and cytokines including CXCL1, which play essential function in MDSC recruitment, were significantly upregulated in EpiCD147-OE transgenic mice." (PMID 35964097, 2022). "Additionally, CXCL1 influenced the angiogenesis process and tumor vasculature, since tube structures were significantly lower after treatment with conditioned media from CXCL1-knockdown T24 cells." (PMID 36699696, 2022). "However, after stopping treatment, neutrophils are recruited to the metastatic liver via CXCL1 and 2 secretion by metastatic tumour cells." (PMID 35022267, 2022). "CXCL1 may also participate in tumor-induced muscle atrophy, one of the components of cancer cachexia." (PMID 35457023, 2022). "In a mouse tumor model, it was shown that radiation therapy triggers the secretion of CXCL1, CXCL2, and CCL5, which leads to neutrophil recruitment to tumor sites; in turn, neutrophils generate ROS and suppress PI3K/AKT/SNAI1 signaling, inhibiting epithelial–mesenchymal transition." (PMID 36555469, 2022). "Using in vitro co-cultures of breast and prostate cancer cells with lymphatic endothelial cells (LEC), Oliveira-Ferrer demonstrated tumor-dependent induction of C3, CFB and C1q secretion as well as that chemokine upregulation (CCL7, CXCL6, CXCL1) by the LECs promotes tumor metastasis." (PMID 35860237, 2022). "Here, early production of CCL2 and CXCL1 may help with shaping the initial myeloid cell compartment in cancer-bearing individuals, which promotes tumour development and production of CCL17 and CXCL10 which in turn modulates recruitment of leukocytes." (PMID 35226704, 2022). "Finally, treatments of AML patient samples ex vivo demonstrated that the combination of a pharmaceutical inhibitor of the NFKB family and GILT can effectively suppress primary blasts’ secretion of tumor-promoting cytokines, such as CXCL1/5/8." (PMID 35625776, 2022). "In addition, prostaglandin E2 promotes tumor growth in vivo by inducing CXCL1 expression, resulting in increased tumor angiogenesis." (PMID 35958781, 2022). "Moreover, CXCL1 neutralizing antibody reduced tumor growth and metastasis of LLC lung carcinoma in vivo." (PMID 36552865, 2022). "Interestingly, the receptor of CXCL1, CXCR2 is elevated in CRC tissue and CXCL1 stimulates tumor growth and increases microvessel density." (PMID 35626056, 2022). "Furthermore, NK cells in tumour tissues produce chemokines, such as CXCL1, CCL5, and FMS-like tyrosine kinase 3 ligands, which affect cDC1." (PMID 36298556, 2022).
tumor (continued). "Tumor cells with a rather high CXCL1 level may also trigger the infiltration of tumor-associated macrophages (TAMs) and cancer-associated fibroblasts (CAF) into the tumor microenvironment." (PMID 35764974, 2022). "For example, silencing CXCL1 resulted in a significant reduction in tumor proliferation through its effect on apoptosis induction in HCC, suggesting that a network of autocrine signals may be involved in CXCL1-associated tumor biology." (PMID 35764974, 2022). "This receptor directs the efflux of myeloid cells from the bone marrow and their migration to tumor sites with high CXCL1 expression, where they promote tumor immune escape by inhibiting the proliferation, activation, and motility of effector T cells and stimulating the expansion of Treg." (PMID 36434686, 2022). "Moreover, they suggested that this miRNA acts as a tumor suppressor through targeting chemokine (C-X-C motif) ligand 1 (CXCL1), which is overexpressed in colorectal cancer and facilitates metastasis and the progression of tumorigenesis." (PMID 35892576, 2022). "CXCL1 can also induce recruitment of regulatory T cells (Treg) and MSCs into the tumor niche." (PMID 35054978, 2022). "In addition, dissection of tumor tissues revealed significant vascular infiltration in tumors of mice overexpressing CXCL1." (PMID 36434686, 2022). "CXCL1, as a chemokine, has been proved to promote tumor progression in a variety of tumors." (PMID 35281077, 2022). "However, the expression of CXCL1 in tumor group was significantly higher than that in the control group." (PMID 35281077, 2022). "Considering the results of gene expression microarray analysis in our previous study, we selected IL-1α, IL-1β, CXCL1, and IL-8 as candidates that may be responsible for tumor-induced osteoclastogenesis (red bars)." (PMID 36614130, 2022). "CXCL1 binds to CXCR2 and has been implicated in tumor growth, angiogenesis, and metastasis." (PMID 33544755, 2021). "Indeed, silencing of CXCL1 levels in tumour cells dramatically retarded tumour growth by preventing the infiltration of neutrophils from peripheral blood into tumour sites." (PMID 33917287, 2021). "Cellular interactions between tumor cells and endothelial, especially the CXCL1/ACKR1 and CXCL8/ACKR1 axes which may recruit ACKR1+ ECs, were enhanced in primary tumor tissues." (PMID 34185421, 2021). "Tumor‐secreted CXCL1 remodeled the formation of iCAF through CXCR2/pSTAT3." (PMID 34218518, 2021). "Two families of chemokines—CC (CCL-2, 3, 5) and CXC (CXCL-1, 2, 5, 6, 8)—employ CCR-2 with monocytes and CXCR-2+ with neutrophils, at the tumour spot which distinguishes between TAMs and tumour-associated neutrophils (TANs), wielding either pro- or antitumour response." (PMID 34336101, 2021). "Importantly, the inhibitory effects on tumour growth and the alterations in TME composition caused by USP12 overexpression were efficiently rescued by CXCL1 and CCL2." (PMID 34381028, 2021). "Additionally, two-way ANOVA demonstrates a significant effect of the tumor on the renal gene expression of Cxcl1, Cxcl9, and Cxcl10." (PMID 34445729, 2021). "We determined that ESCC tumor cells secrete CXCL1 and promote iCAF activation." (PMID 34218518, 2021). "In brief, they found that H3K4me3 modification at the Cxcl1 promoter enhances the expression of CXCL1 in PDA tumor cell clones, leading to low infiltration of T cells and DCs, and the recruitment of MDSCs, which shapes the TIME and influences the outcome of immunotherapy." (PMID 33868269, 2021). "Expression of CXCL1 also recruits T-regs to the tumor microenvironment through CXCR2 signaling." (PMID 34298673, 2021). "We found that single administration of recombinant IL10, CXCL1 or CCL4 attenuates the proliferation of PC cells, and simultaneously induces pro-apoptotic effects, while the stimulation of these cells with a combination of CXCL1/IL10/CCL4 synergistically increased the observed anti-tumour effects." (PMID 34359731, 2021).